NCBP3 (nuclear cap binding subunit 3)
Description:
Associates with NCBP1/CBP80 to form an alternative cap-binding complex (CBC) which plays a key role in mRNA export. NCBP3 serves as adapter protein linking the capped RNAs (m7GpppG-capped RNA) to NCBP1/CBP80. Unlike the conventional CBC with NCBP2 which binds both small nuclear RNA (snRNA) and messenger (mRNA) and is involved in their export from the nucleus, the alternative CBC with NCBP3 does not bind snRNA and associates only with mRNA thereby playing a role in only mRNA export. The alternative CBC is particularly important in cellular stress situations such as virus infections and the NCBP3 activity is critical to inhibit virus growth.
Synonyms: C17orf85; HSA277841; ELG
Tractability: Small molecule: a structure with a bound ligand is known. PROTAC: UniProt records ubiquitination sites on it; ubiquitination databases record sites on it; its protein half-life has been measured.
Gene: Protein-coding gene on chromosome 17 (3,802,158 to 3,846,246, reverse strand). Ensembl gene ENSG00000074356.
Subcellular location: Nucleus; Cytoplasm
Subcellular location (Human Protein Atlas): Nuclear speckles
Gene Ontology:
Molecular function: mRNA binding; protein binding; RNA 7-methylguanosine cap binding; RNA binding; RNA cap binding
Biological process: defense response to virus; mRNA export from nucleus; snRNA export from nucleus; mRNA transcription by RNA polymerase II; regulatory ncRNA-mediated post-transcriptional gene silencing
Cellular component: cytoplasm; nuclear cap binding complex; nucleus; RNA cap binding complex; transcription export complex
Genetic constraint (gnomAD): Loss-of-function variants: 17 observed, 63.15 expected, observed/expected ratio (o/e) 0.27, 90% interval 0.18 to 0.4. The upper end of that interval is the gene's LOEUF score, 0.4, which puts it in group 1 of 6, group 1 being the genes least tolerant of losing a copy. Missense variants: 615 observed, 731.46 expected, observed/expected ratio (o/e) 0.84, 90% interval 0.79 to 0.9. Synonymous variants: 267 observed, 267.67 expected, observed/expected ratio (o/e) 1, 90% interval 0.9 to 1.1.
Homologues: Orthologues: chimpanzee NCBP3 (99% identical), guinea pig NCBP3 (95% identical), pig NCBP3 (95% identical), mouse Ncbp3 (94% identical), rat Ncbp3 (94% identical), rabbit NCBP3 (91% identical), dog NCBP3 (90% identical), tropical clawed frog ncbp3 (68% identical), zebrafish ncbp3 (62% identical).
Diseases named in the same sentence as NCBP3 in open-access papers:
NCBP3 is named in the same sentence as 12 diseases in open-access papers, as found by Europe PMC text mining. Sharing a sentence is not in itself a finding about the gene and the disease. The quoted sentences say what the papers report.
glioma (5 papers, 2021 to 2023). A benign or malignant brain and spinal cord tumor that arises from glial cells (astrocytes, oligodendrocytes, ependymal cells). "NCBP3/SNHG6 promotes tumorigenesis in glioma cells by inhibiting the transcription of GBX2 which is a tumor suppressor." (PMID 37735423, 2023).
viral infections (5 papers, 2015 to 2020). "Associates with NCBP3 to form an alternative CBC, which has a key role in mRNA export and is particularly important in cellular stress situations such as virus infections." (PMID 33051451, 2020). "Here, we show that NCBP3 is required to facilitate translation of cytokine mRNA into functional proteins and to mount a proper immune response during virus infections in vitro." (PMID 31856218, 2019). "In cells growing under steady-state conditions the NCBP1-NCBP2 and NCBP1-NCBP3 complexes functionally overlap, however, NCBP3 has a critical role in clearing viral infections." (PMID 30312682, 2019). "Viral infection experiments suggested regulation of innate immune-response genes in an Ncbp3-dependent manner." (PMID 31856218, 2019). "We employed viral infection, a highly stressful condition requiring a prompt cellular response, to test for the specific role of NCBP3." (PMID 31856218, 2019). "The protein is critical for cells during stress conditions, such as viral infection; a positive impact of NCBP3 on mRNA biogenesis may therefore also provide support in the expression of stress response genes." (PMID 32960271, 2020). "While NCBP3 appeared to be particularly important during viral infections, it may be more broadly involved to ensure proper protein expression." (PMID 31856218, 2019). "Taken together, these data indicated that NCBP3 plays a major role in mounting an antiviral state in response to viral infection, stimulation with a synthetic PRR ligand or treatment with type I interferon and is required for a full-scale antiviral immune response in vitro." (PMID 31856218, 2019). "Notably, NCBP3 becomes pivotal under cellular stress conditions, such as virus infections." (PMID 26382858, 2015). "However, NCBP3 becomes pivotal under stress conditions, such as virus infection." (PMID 26382858, 2015).
acute myocardial infarction (1 paper, 2021). Necrosis of the myocardium, as a result of interruption of the blood supply to the area. "NCBP3 can be considered as a new therapeutic target for acute myocardial infarction prevention." (PMID 34382339, 2021).
lung carcinoma (1 paper, 2022). "Interestingly, NCBP1 is required for capped RNA synthesis and intracellular translation, and has recently been discovered to interact with NCBP3 to induce CUL4B expression, promote lung cancer cell growth, wound healing, migration, and epithelial-mesenchymal transition." (PMID 35982949, 2022).
melanoma (1 paper, 2022). A malignant, usually aggressive tumor composed of atypical, neoplastic melanocytes. "The current research describes for the first time that the risk scores created by EIF4E3, LARP1, NCBP3, and IFIT5 can serve as independent prognostic factors for melanoma." (PMID 36473947, 2022). "To understand the role of m7GMRRGs in melanoma prognosis in further detail, we selected four m7GMRRGs (EIF4E3, LARP1, NCBP3, and IFIT5) to develop prognosis prediction model." (PMID 36473947, 2022).
non-small cell lung carcinoma (1 paper, 2022). A group of at least three distinct histological types of lung cancer, including non-small cell squamous cell carcinoma, adenocarcinoma, and large cell carcinoma. "NCBP3 may act as a bridge between RBPs in the biological function of mRNA, upregulating the expression of downstream target genes in non-small cell lung cancer by interacting with NCBP1, thereby promoting the progression of lung cancer." (PMID 36335189, 2022).
cancer (6 papers, 2022 to 2025). A tumor composed of atypical neoplastic, often pleomorphic cells that invade other tissues. "However, more regulator genes negatively related to those compounds, like AGO2, DCP2, EIF3D, EIF4E, LARP1, and NCBP3 (related to 30 cancer drugs both in GDSC and CTRP), indicating the patients with higher mRNA expression level of these regulator genes might sensitive to these compounds." (PMID 36092891, 2022). "Moreover, NCBP3 showed increased expression in the immune subtype C3, which indicated a better prognosis and longer survival, suggesting that it may have an inhibitory role in cancers." (PMID 36226166, 2022).
tumor (5 papers, 2022 to 2025). "Genes such as EIF4E3, IFIT5, EIF4G3, NUDT16, NUDT10, NCBP3, and NUDT11 showed lower expression in tumor tissues, whereas other genes were highly expressed." (PMID 41406096, 2025). "Only EIF4E3, IFIT5, EIF4G3, NUDT16, NUDT10, NCBP3, and NUDT11 showed decreased expression in tumor tissues." (PMID 41406096, 2025). "Correspondingly, there were some genes that were part of the CAP formation genes, such as NCBP3, NUDT4, CYFIP2, SNUPN, and EIF4E2, which were weakly expressed in most tumor tissues and highly expressed in normal tissues." (PMID 36226166, 2022).
infection (1 paper, 2019). The state of being infected such as from the introduction of a foreign agent such as serum, vaccine, antigenic substance or organism. "In vitro, infections with RNA viruses resulted in elevated viral titers, increased viral protein production as well as in higher viral transcript expression in Ncbp3-deficient cells." (PMID 31856218, 2019). "However, IAV infection resulted in high mortality of Ncbp3-deficient mice of which 66.7% had to be euthanized for animal welfare reasons within 13 days of infection." (PMID 31856218, 2019). "RNA of the housekeeping gene Hmbs was similarly expressed upon infection and in Ncbp3-ko compared to wt cells, supporting our previous observations that generic mRNA maturation is not affected by the absence of NCBP3." (PMID 31856218, 2019). "Such a function of NCBP3 would be predominantly important in the early stages of infection in vivo, when little virus stimulus triggers an antiviral response, and unimpaired execution of antiviral programs is required to control initial infection." (PMID 31856218, 2019). "Notably, infection with different doses of an IAV reporter virus expressing renilla luciferase showed that Ncbp3-/- MEFs allowed increased IAV-renilla reporter activity as compared to Ncbp3+/+ MEFs." (PMID 31856218, 2019). "In order to further study viral activation of innate immune pathways potentially dependent on Ncbp3, we quantified amounts of secreted IRF- and NF-κB-regulated cytokines IP-10 and IL-6 upon infection of MEFs with IAV-ΔNS1." (PMID 31856218, 2019). "Altogether, these data show that infection with unrelated RNA viruses, regardless of their replication site, results in higher accumulation of viral particles in supernatant of NCBP3-depleted cells." (PMID 31856218, 2019).
NCBP3 also shares sentences with these, for which no sentence is quoted: prostate carcinoma (2 papers); breast carcinoma (1); endometrial carcinoma (1).